NR3C1 (nuclear receptor subfamily 3 group C member 1)
Diseases named in the same sentence as NR3C1 in open-access papers (continued):
Sharing a sentence is not in itself a finding about the gene and the disease.
depression (continued). "It has been suggested that the susceptibility of MAOA-L females to depression may be a result of epigenetic dysregulation of MAOA by early life stressors, which affects DNA methylation of the glucocorticoid receptor gene NR3C1." (PMID 33584798, 2020). "Summing up, ACS patients with both NR3C1 hypermethylation and depressive disorder may be liable to poor prognosis through a combination of biological and behavioural factors." (PMID 32218512, 2020). "Exon 1F of NR3C1 has been extensively studied with regards to its role in early life adversity, and has been the target of focus for many depression studies as well." (PMID 31019524, 2019). "The study findings indicate that the level of neonatal NR3C1 DNAm was related to later social-emotional functioning, and the effect persisted after adjustment for other predictors of development (i.e., maternal smoking, depression and dose of HV service)." (PMID 30804765, 2019). "However, the expression of Nr3c1 which helps mediate executive functions, including depression and stress-related emotion and biochronometer activities, was significantly higher in the PFC of SHRs than in WKY rats." (PMID 26820676, 2017). "Furthermore, differences between MDD and BPD were seen for matrix-associated growth factors APP and SPARC, immune gene TNF, and transcription factors CREB1, NFKB1, and NR3C1 when controlling for depression severity, age, and medication use." (PMID 24143878, 2013). "Furthermore, the gene encoding the glucocorticoid receptor (NR3C1) has been shown to undergo increased methylation in response to stress, leading to impaired stress response mechanisms and heightened vulnerability to depression." (PMID 40004109, 2025). "In MDD, hypermethylation of NR3C1 promoter regions in individuals with childhood trauma is associated with reduced GR expression and dysregulation of the HPA axis, a hallmark of depression." (PMID 41234420, 2025). "Furthermore, methylation of the NR3C1 gene could be predicted by a history of childhood abuse or major depressive disorder." (PMID 38792892, 2024). "Finally, the interaction term relating to current distress level due to each interpersonal traumatic event and each NR3C1 CpG site in relation to personality vulnerability to depression was significant on CpG 3 and 4 (B = 0.50, CI95% 0.01–0.60, B = 0.70, CI95% 0.16–1.24, respectively)." (PMID 39257475, 2024). "In this study, we examined the joint contribution of Pb and depression occurring during gestation in relation to birth outcomes, and considered NR3C1 methylation as a potential shared biological mechanism that may help explain how these environmental and psychosocial factors influence infant health." (PMID 34831923, 2021). "Also in a study conducted on a group of early school-age children who were diagnosed with depression in the prenatal period, a reduced methylation of the glucocorticoid receptor (NR3C1) gene, mineralocorticoid receptor (NR3C2) gene and the serotonin receptor (SLC6A4) gene were indicated." (PMID 33385173, 2021). "In humans, it has recently been suggested that epigenetic mechanisms, including NR3C1 regulation, might differ between males and females, with a sex-dependent role of NR3C1’s methylation in depression, but also a sex-specific effect of allelic variation of the NR3C1 gene." (PMID 32754072, 2020). "Therefore, ELS probably altered the epigenetic profile of the NR3C1, but whether this change mediated the association between ELS and depression is in debate." (PMID 33117794, 2020). "Co-occurrence of asthma, mood disorders and anxiety may stem from a common genetic cause; this has been indirectly confirmed by the evidence that gene polymorphisms are associated with the occurrence of NR3C1 mood disorders, and also that the HPA axis is involved in the pathogenesis of depression." (PMID 25009637, 2014).
depression (continued). "Mutaz Amin's team has successively revealed the role of nuclear receptor subfamily 3 Group C member (NR3C1) Gene, corticotropin‐releasing hormone receptor 2 (CRHR2) Gene, and Melanocortin Receptor Genes in the comorbidity of familial diabetes and depression." (PMID 40820550, 2025). "In depression, altered chromatin accessibility have been observed at BDNF, GAD1, NR3C1 in response to stress." (PMID 41234420, 2025). "In a study of patients with major depressive disorder of European ancestry, the interaction of FKBP5, SKA2, and NR3C1 genes with CT in SA was analyzed, showing a significant interaction between FKBP5 and CT." (PMID 41300231, 2025). "We examined individual differences in the DNA methylation patterns within the GR receptor NR3C1 and the FKBP5 gene in order to characterize epigenetic markers of personality vulnerability to depression, resilience, and perinatal depressive symptoms." (PMID 39257475, 2024). "Some of the common down genes in maternal C57 mice and depression were for the MAP kinase pathway and some of the common down genes included: FOS, EGR1, DUSP1, BDNF, NR4A1, NR3C1, the neuropeptide somatostatin (SST), and one of the its receptors, SSTR2." (PMID 34997033, 2022). "Notable downregulated genes matching depression were: BDNF, the glucocorticoid receptor, NR3C1, and activity related genes, EGR1, FOS, NR4A1, FOSB, and ARC." (PMID 34997033, 2022). "A review on DNA methylation in depression demonstrated a connection between depression and methylation of BDNF and NR3C1 genes, while the correlation of SLC6A4 with depression was conflicted." (PMID 35807931, 2022). "Furthermore, anxiety and depression are important prodromal symptoms in the emergence of psychosis, and allelic variations in the NR3C1 gene have been found associated with depression, with or without psychotic features, as well as with cognitive deterioration, independently of cortisol levels." (PMID 32754072, 2020). "Candidate genes of DNA methylation, such as NR3C1, SLC6A4, and BDNF, have been regarded as potential biomarkers of depression." (PMID 32256396, 2020). "NR3C1 methylation tests might have clinical implications in screening for epigenetic susceptibility to identify high risk groups of poor ACS prognosis; therefore, this status serves as a promising prognostic biomarker in these patients particularly with the diagnosis of depressive disorders." (PMID 32218512, 2020). "Compared to out-of-the-country controls and their children, genocide survivors and their children had higher levels of PTSD and depression, lower cortisol levels, and higher DNA methylation of the promoter of NR3C1 (a glucocorticoid receptor)." (PMID 30781888, 2019). "Studies on NR3C1, OXTR, and other candidate genes reported mixed findings in terms of methylation modification and depression." (PMID 30718449, 2019). "Changes in NR3C1 gene expression in blood have also been detected, with some studies identifying increased expression in patients with depression and others finding a negative correlation with depressive scores." (PMID 40018685, 2025). "Compared to infants with mothers who did not report depression, infants of depressed mothers with greater placental NR3C1 CpG2 methylation demonstrated poorer self-regulation, more hypotonia, and more lethargy on neurobehavioral assessments." (PMID 38676353, 2024). "We examined differences in DNA methylation patterns in the NR3C1 and FKBP5 genes in relation to personality vulnerability to depression, resilience, and perinatal depressive symptoms, whilst also considering possible moderating effects of childhood traumatic events." (PMID 39257475, 2024). "We were not able to replicate the findings reported for the NR3C1 and MAOA genes, for which DNAm levels were found to explain the maltreatment-depression association." (PMID 36634080, 2023).
depression (continued). "The relationship between NR3C1 methylation and depression has been validated in studies of mothers and their infants, with children of mothers with depression having higher DNA methylation of NR3C1 gene than children of mothers without depression." (PMID 36091061, 2022). "Despite these parallel sets of studies, researchers have not considered gestational Pb and depression exposures as jointly modulating NR3C1 methylation." (PMID 34831923, 2021). "We have shown that alcohol consumption, overweight, and high cortisol levels are related to NR3C1 non-methylation, while depression is related to its methylation." (PMID 33762648, 2021). "The association between TESI and the SNPs rs737054 (TT genotype) in FKBP5 and rs2963155 (GG/AG genotypes) in NR3C1 did not remain significant after adjustment for depression severity changes." (PMID 32952155, 2020). "For this purpose, we aim to investigate the estrogen receptor genes (ER1, ER2, GPER), the glucocorticoid receptor (NR3C1) as well as the serotonin transporter (5-HTTLPR) and the respective relationships with a resilient menopausal transition or the development of depression in the perimenopause." (PMID 32699639, 2020). "In conclusion, higher NR3C1 methylation status at early phase of ACS predicted worse long-term prognosis of ACS in the presence of depressive disorder, independent of potential confounders including important cardiovascular risk markers." (PMID 32218512, 2020). "For boys, by contrast, anxious-depressed symptoms were not predicted by the prenatal and postnatal depression interaction term (p = 0.920), and the effect on NR3C1 methylation was smaller than for girls, though still significant (p = 0.003)." (PMID 31438539, 2019). "Their symptoms and NR3C1 methylation levels were higher when their mothers had reported low levels of depression during pregnancy, in line with the idea that they had not been prepared by the fetal environment for postnatal exposure to maternal depression." (PMID 31438539, 2019). "For instance, the glucocorticoid receptor gene (NR3C1) SNP rs6195 was related to depression among females, but not males." (PMID 30967802, 2019). "Haplotype analysis performed using the additive haplotype effects model [global statistic, 0.913; degrees of freedom (DF), 6; P=0.988] did not reveal any correlations between the NR3C1 gene haplotypes and depression, as shown in Table VII." (PMID 25009637, 2014). "In addition, as expected, several targets (NR3C1, GSK3B, EGM_09788) with high scores were related to depression and age-related decline." (PMID 25105297, 2014). "Given the literature on the NR3C1 gene and depression as well as on the HPA-axis, it is not surprising that this SNP can be linked to the hippocampus structure and the personality dimension neuroticism." (PMID 23761749, 2013). "A recent examination of post-mortem brain from donors with major depression (but without documented child abuse) found reduced expression of hippocampal NR3C1 exon 1F." (PMID 22295073, 2012). "The down-regulation or decreased expression of the glucocorticoid receptor gene, namely NR3C1, has been widely observed in early life stress (ELS) or early life adversity (ELA), which lead to psychopathologic conditions such as major depressive disorders in adolescence and adulthood." (PMID 31717711, 2019). "Indeed, a number of recent studies have reported that genes known to be implicated in depression, such as SLC6A4, NR3C1 and BDNF, are differentially methylated in peripheral blood and/or buccal cells of individuals with depression, compared to those without." (PMID 29070016, 2017). "In conclusion we could not show an association between depression measurements as assessed by EPDS values during or after pregnancy and candidate haplotypes in the genes FKBP5, NR3C1, and CRHR1." (PMID 24741566, 2014).
depression (continued). "DNA methylation of NR3C1 and FKBP5 was not significantly correlated with personality vulnerability to depression, resilience levels, or with perinatal depressive symptoms." (PMID 39257475, 2024). "There were no other group differences in NR3C1 CpGs and FKBP5 methylation in relation to the outcomes (resilience, depressive symptoms, and personality vulnerability to depression)." (PMID 39257475, 2024). "In the present study, we aimed to investigate whether NR3C1 methylation status was correlated with known cardiovascular markers at the early phase of ACS, and whether it was associated with the long-term prognosis of ACS considering the negative impact of depression on these outcomes." (PMID 32218512, 2020). "However, the role of NR3C1 methylation on prognosis of ACS has not been investigated, despite the clinical importance of depression-ACS comorbidity." (PMID 32218512, 2020). "Therefore, though most studies supported that ELS increased the NR3C1 DNAm and possibly that the epigenetic alterations resulted in a blunt HPA axis, emerging evidence indicated that even ELS altered NR3C1 DNAm, this molecular change may not be powerful enough to develop depression." (PMID 33117794, 2020).
Anxiety (146 papers, 2008 to 2026). Intense feelings of nervousness, tension, or panic often arise in response to interpersonal stresses. "The expression of the nr3c1 and nr3c2 genes, which encode glucocorticoid and mineralocorticoid receptors, respectively, also plays a critical role in regulating stress and anxiety-related behaviors." (PMID 40243462, 2025). "We discussed earlier the example of the hypermethylation of the NR3C1 gene, a glucocorticoid receptor gene in new-borns that has been repeatedly associated with maternal depression/anxiety during pregnancy." (PMID 40649875, 2025). "Previous studies have demonstrated that hypermethylation of the NR3C1 gene is associated with internalizing psychopathologies such as anxiety or depression." (PMID 37254074, 2023). "Methylation of NR3C1 glucocorticoid receptor (GR) gene is associated with depression, post-traumatic stress and anxiety." (PMID 37373281, 2023). "This study aimed to investigate the association between NR3C1 gene methylation, academic pressure, and anxiety symptoms among Chinese adolescents." (PMID 37254074, 2023). "Our findings suggest that increased methylation of NR3C1-16 CpG10 was associated with both persistent anxiety symptoms and academic pressure." (PMID 37254074, 2023). "In a sample of pregnant women (N = 83) from Belgium, psychosocial stress and cortisol was measured at each trimester, and pregnancy-related anxiety was found to be associated with NR3C1 methylation in cord blood." (PMID 37987302, 2023). "A second study indicated that pregnancy-specific anxiety in the first and second trimesters is linked to epigenetic changes in the NR3C1 promoter among the newborns." (PMID 36768104, 2023). "Our novel finding of a significant association between academic pressure and NR3C1 methylation level change highlights the potential role of DNA methylation in anxiety etiology." (PMID 37254074, 2023). "Low-level maternal care-induced anxiety-related behavior in adulthood was associated with reduced H3K9ac levels at the glucocorticoid receptor gene (Nr3c1) in rats." (PMID 36358910, 2022). "The higher maternal anxiety during the third trimester, the higher the methylation of the NR3C1-CpG3, which was subsequently, associated with lower children’s ADHD traits." (PMID 34572069, 2021). "All studies examined exon 1F, and two studies found an association between 3rd trimester anxiety and newborn NR3C1 hypermethylation at CpG2 within exon 1F." (PMID 34299914, 2021). "Higher maternal anxiety during the third trimester was associated with more methylation levels of the NR3C1." (PMID 34572069, 2021). "The higher maternal anxiety during the third trimester, the greater the methylation of the NR3C1-CpG1, which in turn was then associated with lower anxiety symptoms in the children." (PMID 34572069, 2021). "Gestational age at birth was significantly (p < 0.05) associated with maternal anxiety during the second trimester, DNA methylation of NR3C1-CpG8, and DSM attention deficit/hyperactivity problems." (PMID 34572069, 2021). "Our data suggest broad and physiologically pertinent changes in DNA methylation in placenta that correlate with anxiety-like behavior in adulthood in response to Nr3c1 deficiency." (PMID 30655507, 2019). "This study presents evidence of reduced methylation of NR3C1 in association with childhood maltreatment and depressive, anxiety and substance-use disorders in adults." (PMID 27378548, 2016). "In an Australian birth cohort (Barwon Infant Study), maternal depression and anxiety at 28 weeks’ gestation were nominally associated with increased DNA methylation of different sites in the NR3C1 1F promoter region in cord blood mononuclear cells." (PMID 27918480, 2016). "In further support of a role for glucocorticoid-system mediated alterations with PTSD, additional work has revealed a role for epigenetic regulation of the gene encoding the GR Nr3c1, and its polymorphism Bcl1 in fear, stress, and anxiety." (PMID 23847551, 2013).